MYH1 (myosin heavy chain 1)
Description:
Required for normal hearing. It plays a role in cochlear amplification of auditory stimuli, likely through the positive regulation of prestin (SLC26A5) activity and outer hair cell (OHC) electromotility.
Synonyms: MyHC-2x; MYHSA1; MYHa; MyHC-2X/D; MGC133384; HEL71
Tractability: PROTAC: ubiquitination databases record sites on it.
Gene: Protein-coding gene on chromosome 17 (10,491,389 to 10,518,719, reverse strand). Ensembl gene ENSG00000109061.
Subcellular location: Cytoplasm, myofibril
Subcellular location (Human Protein Atlas): Focal adhesion sites
Gene Ontology:
Molecular function: protein binding; actin filament binding; microfilament motor activity; ATP binding; cytoskeletal motor activity
Biological process: sensory perception of sound; actin filament-based movement; muscle contraction
Cellular component: cytoplasmic ribonucleoprotein granule; muscle myosin complex; cytoplasm; myosin filament; myosin II complex; sarcomere; A band; intercalated disc; myofibril; myosin complex; supramolecular fiber
Genetic constraint (gnomAD): Loss-of-function variants: 214 observed, 231.61 expected, observed/expected ratio (o/e) 0.92, 90% interval 0.83 to 1.03. The upper end of that interval is the gene's LOEUF score, 1.03, which puts it in group 4 of 6, group 1 being the genes least tolerant of losing a copy. Missense variants: 2,098 observed, 2,427.1 expected, observed/expected ratio (o/e) 0.86, 90% interval 0.83 to 0.9. Synonymous variants: 774 observed, 871.12 expected, observed/expected ratio (o/e) 0.89, 90% interval 0.84 to 0.94.
Homologues: Orthologues: chimpanzee MYH1 (99% identical), pig MYH1 (97% identical), dog MYH1 (97% identical), rat Myh1 (97% identical), mouse Myh1 (97% identical), rabbit MYH1 (97% identical), guinea pig MYH1 (94% identical). Paralogues in human: MYH2 (95% identical), MYH4 (94% identical), MYH8 (92% identical), MYH3 (84% identical), MYH13 (82% identical), MYH7 (81% identical), MYH6 (81% identical), MYH7B (67% identical), MYH15 (59% identical), MYH11 (42% identical), MYH9 (41% identical), MYH10 (41% identical), and 32 more.
Diseases named in the same sentence as MYH1 in open-access papers:
MYH1 is named in the same sentence as 48 diseases in open-access papers, as found by Europe PMC text mining. Sharing a sentence is not in itself a finding about the gene and the disease. The quoted sentences say what the papers report.
breast carcinoma (5 papers, 2008 to 2024). "Our current study demonstrate that genes involved in myogenesis (i.e., Pax7 and Myod) and muscle function (i.e., Myh1 and Pdk4), as well as miR-486, a regulator of myogenesis, are uniquely dysregulated in skeletal muscles based on breast cancer subtype and mutation pattern." (PMID 38651826, 2024). "For instance, breast cancer cell-derived exosomes could induce muscle catabolism of mature muscle cells, leading to loss of myosin heavy chain 1 (MYH1) and myotube atrophy." (PMID 38689293, 2024). "Recently, MYH1 encoding skeletal muscle myosin heavy polypeptide 1 and MYH9 encoding non-muscle myosin heavy chain type A, were identified as candidate breast cancer genes in systematic analyses of the breast cancer genome." (PMID 18796164, 2008). "Recently, MYH1 and MYH9 have been identified as candidate breast cancer genes in a systematic analysis of the breast cancer genome." (PMID 18796164, 2008).
cardiomyopathies (3 papers, 2013 to 2025). "Comparatively, a vast number of different human myopathies including cardiomyopathies are caused by mutations in one of the many cytoskeletal sarcomeric proteins, of which MYH1 is one." (PMID 37938355, 2024). "Lungs from VIP−/− mice showed overexpression of cardiomyopathy genes: Myh1 was upregulated 224 times over WT, and Mylpf was increased 72 fold." (PMID 23700405, 2013). "MYH1 expression has been found to be significantly up-regulated in mice with cardiomyopathy." (PMID 37938355, 2024).
Obesity (3 papers, 2017 to 2024). Accumulation of substantial excess body fat. "Correlation analysis between metabolites and genes indicated a negative association between saturated fatty acids and Myh1, 2, and 4 expressions, suggesting their role in obesity related inactivity‐induced muscle atrophy." (PMID 39001701, 2024). "Meta-analysis of data related to RQ1 (“pathological decline associated with obesity, insulin resistance or type 2 diabetes mellitus”) revealed a significant increase in the abundance of fast-twitch myosin heavy chain isoforms (MYH1 and MYH2) in obesity and T2DM." (PMID 29137117, 2017).
type 2 diabetes (3 papers, 2013 to 2017). "It has been reported that in obese and type 2 diabetics there is an inverse relationship between insulin sensitivity and the percent of myosin heavy chain IIx (MYH1)." (PMID 23805253, 2013).
skeletal myopathies (2 papers, 2022 to 2025). "No human skeletal myopathy has so far been described to be caused by variants in MYH1, encoding fast, type 2X MyHC protein, which is expressed in type 2B fibers." (PMID 36380287, 2022).
and lung carcinoma (1 paper, 2022). "MYH1 was selected because it forms a highly differentially methylated cluster and is known to show aberrant expression levels in aggressive cells in head and neck squamous and lung carcinoma tumours." (PMID 36125262, 2022).
autoimmune disease (1 paper, 2018). A disorder resulting from loss of function or tissue destruction of an organ or multiple organs, arising from humoral or cellular immune responses of the individual to their own tissue constituents. "This is the first report of a mutation in MYH1 and the first link between a skeletal muscle myosin mutation and autoimmune disease." (PMID 29510741, 2018).
Autoimmunity (1 paper, 2018). The occurrence of an immune reaction against the organism's own cells or tissues. "The loss of hydrogen bonds with the MYH1 mutation could possibly lead to conformational changes in myosin that activate TLRs and autoimmunity." (PMID 29510741, 2018).
cervical cancer (1 paper, 2023). A primary or metastatic malignant neoplasm involving the cervix. "The results showed that high expression of MYH1, MYH4, FGG, and DEPP1 was associated with shorter overall survival of patients with cervical cancer; high expression of SULT1E1, RAB3C, CXCR3, and PROX2 was associated with longer overall survival of patients with cervical cancer." (PMID 37350944, 2023). "High expression of MYH1, MYH4, FGG, DEPP1, and ZBTB16 was associated with shorter overall survival of patients with cervical cancer; high expression of SULT1E1, RAB3C, CXCR3, and PROX2 was associated with longer overall survival of patients with cervical cancer." (PMID 37350944, 2023).
deafness (1 paper, 2024). An inherited or acquired condition characterized by the complete loss of the ability to hear from one or both ears. "Myh1, which encodes myosin heavy chain 1, is a mouse deafness gene and constitutes a crucial component of myosin II, a hexameric actin-based motor protein that transforms chemical energy into mechanical force through ATP hydrolysis." (PMID 39482536, 2024).
developmental delay (1 paper, 2024). "Data provided in gnomAD revealed two South Asian individuals homozygous for one of the MYH1 variants (c.868C > T; p.Arg290Cys), suggesting that this variant is unlikely to cause a severe phenotype, such as global developmental delay." (PMID 39482536, 2024).
dilated cardiomyopathy (1 paper, 2018). Cardiomyopathy which is characterized by dilation and contractile dysfunction of the left and right ventricles. "In contrast to the low frequency of mutations in MYH1 and MYH2, more than 500 disease-causing point mutations have been described in MYH7, with the majority producing hypertrophic or dilated cardiomyopathy." (PMID 29510741, 2018).
hearing loss (1 paper, 2024). "We questioned whether the MYH1 variants identified in individuals with hearing loss were structurally different from the wild-type protein." (PMID 39482536, 2024). "We analyzed whole-exome sequencing data from 437 patients with hearing loss of unknown genetic causes and identified biallelic missense variants of MYH1 in five unrelated families." (PMID 39482536, 2024).
idiopathic pulmonary fibrosis (1 paper, 2022). Idiopathic pulmonary fibrosis (IPF) is a nonneoplastic pulmonary disease that is characterized by the formation of scar tissue within the lungs in the absence of any known cause. "Interestingly, expression of MYH1 has previously been found to be upregulated in the bleomycin mouse model of idiopathic pulmonary fibrosis (IPF)." (PMID 36675685, 2022).
leiomyosarcoma (1 paper, 2020). An uncommon, aggressive malignant smooth muscle neoplasm, usually occurring in post-menopausal women. "The downregulation of skeletal myosins (MYH1, MYH2, MYH4) by bortezomib is not easily explained, since skeletal myosins are typically markers of rhabdomyosarcoma rather than leiomyosarcoma." (PMID 32117764, 2020).
myositis (1 paper, 2018). "Because both the DBA/2 MYH7 mutation and the equine MYH1 variant are located in the globular head of myosin, it is possible that a mutation in this highly conserved region somehow confers target host susceptibility to myositis." (PMID 29510741, 2018).
osteochondritis dissecans (1 paper, 2022). A rare bone disease characterized by an acquired idiopathic necrotic lesion of subchondral bone with the formation of a sequestrum, which may detach to form loose bodies in joints. "A novel association was identified between MYH1 and osteochondritis dissecans (p = 1.01 × 10−7), involving a variant predicted as pathogenic by seven predictors; MYH1 is involved in skeletal muscle and has been linked to rhabdomyolysis." (PMID 35945607, 2022).
Osteopenia (1 paper, 2024). Osteopenia is a term to define bone density that is not normal but also not as low as osteoporosis. "Three of five individuals with MYH1 variants displayed osteopenia." (PMID 39482536, 2024). "Notably, three of the five patients also exhibited osteopenia, mirroring the reduced bone mineral density observed in Myh1-KO mice." (PMID 39482536, 2024).
rhabdomyolysis (1 paper, 2021). Necrosis or disintegration of skeletal muscle often followed by myoglobinuria. "In the present study, we have focused our attention on a MYH1-related E321G amino acid substitution within the head region of the type IIx skeletal myosin heavy chain, associated with clinical signs of atrophy, inflammation and/or profound rhabdomyolysis, known as equine myosin heavy chain myopathy." (PMID 34943936, 2021). "Additionally, in future experiments, we should assess how our findings relate to newly reported MYH1-related human rhabdomyolysis cases." (PMID 34943936, 2021).
sebaceous tumors (1 paper, 2023).
sensorineural hearing loss (1 paper, 2024). "After applying the variant filtering criteria, we identified eight different biallelic variants in MYH1 (myosin heavy chain 1; MIM: 16073) in five probands who were diagnosed with a recessive form of sensorineural hearing loss." (PMID 39482536, 2024).
Sepsis (1 paper, 2025). Sepsis is defined as life-threatening organ dysfunction caused by a dysregulated host response to infection. "Sepsis upregulated the expression of Myh1 in all groups (P < 0.001), whereas only rAAV-shIlk1 mice displayed increased Myh2 mRNA expression (P < 0.05)." (PMID 41385533, 2025).
Stroke (1 paper, 2019). Sudden impairment of blood flow to a part of the brain due to occlusion or rupture of an artery to the brain. "Our proteomics results show that many cytoskeletal proteins were present at higher-than-normal concentrations in CSF following stroke, including myosins (MYH1/4/8/9 and MYL1), and tubulins (TUBA1A/B/C, TUBA3A, and TUBB4A/B)." (PMID 30645580, 2019).
cancer (14 papers, 2012 to 2025). A tumor composed of atypical neoplastic, often pleomorphic cells that invade other tissues. "Through pan-cancer analysis, we found that MYH1, MYH2, and MYH7 are dysregulated in cancers, including HNSC." (PMID 37340028, 2023). "On this basis, MYH11 mutations may increase cell migration and adhesion by altering MYH1 function (motility and energy dysregulation) in affected cancer cells." (PMID 37598251, 2023). "Interestingly, tumour‐induced alterations in the expression of Atrogin1, MuRF1, Pik3r1, Pdk4, Myh4, Myh2 and Myh1 were attenuated in EDA2R‐deficient muscles, implying that the EDA2R pathway contributes to the reprogramming of muscle gene expression during cancer cachexia." (PMID 39001644, 2024). "We can observe that although MYH1, MYH2, and MYH7 were dysregulated in some of the cancers, their expression levels are very low, except for HNSC." (PMID 37340028, 2023). "Polymorphisms were also found in other canonical cancer-related genes, including SLC37A3, BAZ1A, SRP54, MYH1 and ABCC1, but were not directly involved in MASLD pathogenesis." (PMID 38540416, 2024). "We found seven upregulated genes (MCM10, RAD51-associated protein 1 (RAD51AP1), KIF2C, Y_RNA, FAM64A, CDC6, and CDCA8) and six downregulated genes (ADAMTS8, ATP1A2, MYH1, OGN, OMD, and ZBTB16) in at least two phenotypes containing either ALT high/middle or TEL high/middle regardless the cancer type." (PMID 38763334, 2024). "In addition to the microtubule-interacting kinesins, we identified three actin-binding proteins, MYH1, MYO1G and TPM2, as essential proteins for cancer cell survival." (PMID 23071517, 2012). "In this study, we identified KIF11, KIF20A, KIF21, KIF25, MYO1G, MYH1 and TPM2 as proteins whose depletion causes growth inhibition and non-apoptotic cell death in cancer cells." (PMID 23071517, 2012).
myopathies (7 papers, 2018 to 2025). "MYH1 (AUC: 0.856) achieved the maximum diagnostic value in RYR1 mutation-associated myopathies samples, and the diagnostic values of other genes included the following: TNNT3 (AUC: 0.840), MYLPF (AUC: 0.786), and ATP2A1 (AUC: 0.765)." (PMID 35692882, 2022). "This is the first report of a mutation in MYH1 gene associated with susceptibility to a specific myopathy." (PMID 29510741, 2018). "The ROC curve analysis showed that MYH1, ATP2A1, TNNT3, and MYLPF showed good diagnostic performance for RYR1 mutation-associated myopathies." (PMID 35692882, 2022). "Abnormal expression of MYH1 is closely related to muscle diseases, so MYH1 is of great significance in explaining the pathogenesis, development, and diagnosis of RYR1 mutation-associated myopathies." (PMID 35692882, 2022). "Impacted by their good diagnostic properties in RYR1 mutation-associated myopathies, a hypothesis was proposed that MYH1, ATP2A1, TNNT3, and MYLPF are likely to serve as biomarkers for diagnosing RYR1 mutation-associated myopathies." (PMID 35692882, 2022). "Four skeletal muscle tissue-specific genes were identified, including MYH1, TNNT3, MYLPF, and ATP2A1, as the potential biomarkers for diagnosing and treating RYR1 mutation-associated myopathies, which provided insights into the transcriptome-level development mechanism." (PMID 35692882, 2022). "Together, our results suggest that rather than consistently causing a myopathy, homozygosity and, in some cases, heterozygosity for the MYH1 variant predisposed horses to a myopathy under certain environmental triggers." (PMID 29510741, 2018). "Thus far, MYH1 has not been associated with RYR1 mutation-associated myopathies, but it has been found in studies on other muscle diseases that MYH1 mutations in humans and horses are closely related to recurrent rhabdomyolysis." (PMID 35692882, 2022). "The nine horses lacking the MYH1 E321G variant could very well represent phenocopies due to an inflammatory myopathy." (PMID 29510741, 2018). "MYH1, a cytoskeletal muscular protein interacting with actin, has not been clearly associated with RYR1-related myopathies." (PMID 39273074, 2024).
tumor (7 papers, 2019 to 2024). "The tumor displayed a strong activation of genes for mesodermal (Desmin, Myog, Myh1 and Myh3) and endodermal (Afp, Krt20) tissue differentiation." (PMID 33468253, 2021). "Four genes (MYH1, PCDHB16, PCDHB15, and BCL2L10) showed a differential methylation profile between metastatic and primary tumour tissue samples (data not shown)." (PMID 36125262, 2022).
MYH1 also shares sentences with these, for which no sentence is quoted: lung adenocarcinoma (2 papers); amyotrophic lateral sclerosis (1); congenital myopathies (1); Duchenne muscular dystrophy (1); epilepsy (1); glioma (1); glycogenosis (1); gout (1); infantile spasms (1); infection (1); Insulin resistance (1); kidney-disease (1); leukemia (1); liver cancer (1); melanoma (1); metabolic disease (1); muscular dystrophies (1); nemaline myopathy (1); prediabetes (1); rhabdomyosarcoma (1); stomach adenocarcinoma (1); type 2 diabetes mellitus (1).